GSDMB (gasdermin B)
Diseases named in the same sentence as GSDMB in open-access papers (continued):
Sharing a sentence is not in itself a finding about the gene and the disease.
cancer (102 papers, 2011 to 2026). A tumor composed of atypical neoplastic, often pleomorphic cells that invade other tissues. "Further research is needed to understand how cancer-associated pyroptosis, mediated by GSDMB, C, and E, is regulated." (PMID 40573305, 2025). "The GSDMB staining patterns are linked to its role in cancer progression, the immune microenvironment, systemic inflammatory response, chemotherapeutic efficacy, and prognosis." (PMID 38711020, 2024). "In our study, we found that the different subcellular localization of GSDMB were associated with diverse cancer progression and immune response." (PMID 38711020, 2024). "The regulation of IAP has been extensively studied, but how cancer-associated pyroptosis, mediated by GSDMB, C, and E, is regulated remains elusive and awaits further investigation." (PMID 36742298, 2023). "GSDMB is implicated in many physiological and pathogenic processes, suggesting the versatile nature of GSDMB in primates, thereby making it a promising target for cancer and antimicrobial therapeutics." (PMID 36599845, 2023). "Taken together, no potential association was found between the genetic alteration of GSDMB and the clinical survival prognosis of different cancers." (PMID 37064151, 2023). "After p-value adjustment, the cancer types significantly associated with GSDMB were ACC, BLCA, DLBC, KICH, KIRC, LAML, PAAD, and SKCM." (PMID 35922531, 2022). "According to our findings, overexpression of GSDMB was also associated with poor prognosis in several cancers." (PMID 35922531, 2022). "Summarizing, future studies comparing the different GSDMB isoform GEMMs would be required to identify the precise functions of each GSDMB variant in cancer and other diseases." (PMID 35281099, 2022). "Low expression of both gasdermin B and E is associated with poor survival in various cancers, including breast cancer, bladder cancer, and melanoma." (PMID 35401556, 2022). "Our pan-cancer analysis indicates that the expression of GSDM genes (in particular GSDMB, GSDMC, and GSDMD) was significantly associated with the survival of patients with certain types of urinary tract system cancer." (PMID 36003332, 2022). "GSDMB, encoding the protein gasdermin B, a member of the cancer-associated gasdermin-domain-containing protein family implicated in cancer pathogenesis, is adjacent to ORMDL3 on chromosome 17." (PMID 21985515, 2011). "The GSDMB expression in cancer cells is associated with systemic inflammatory response." (PMID 38711020, 2024). "Elevated GSDMB levels are associated with the onset and progression of cervical squamous cell tumors, potentially enhancing their proliferation and hastening the spread of early-stage cancer cells." (PMID 38304430, 2024). "While recent reports indicate that these variants could mediate different effects both in cancer and inflammatory diseases, their precise regulatory mechanisms and their involvement in pyroptosis and other GSDMB functions is largely unknown." (PMID 36899106, 2023). "Additionally, the “Clinical” module of TISIDB was used to analyze the association between GSDMB and the clinical progression (stage) of different cancers." (PMID 37064151, 2023). "Considering this potential association between GSDMB isoforms and cancer survival, further studies are warranted to explore whether cancer cells exploit differential expression of GSDMB isoforms to resist attack by cytotoxic lymphocytes." (PMID 36991122, 2023). "Four GSDMB splice variants have been identified and each one could have a unique function in cancer." (PMID 36119049, 2022). "Whether GSDMB cell death-independent activity might contribute to GSDMB-associated cancer cell growth in some contexts remains to be fully investigated, although it has been speculated that GSDMB binding to signaling lipids may impart non-pyroptotic functions." (PMID 35608339, 2022).
cancer (continued). "Additionally, inducing pyroptosis in cancer cells expressing pyroptosis‐activable GSDMB variants could represent a promising therapeutic strategy." (PMID 40783818, 2025). "In addition to bacterial infection, GSDMB is associated with various cancers." (PMID 36991122, 2023). "It details the roles of GSDMB in cancers, autoimmune and inflammatory diseases, as well as bacterial/viral infectious diseases, as evidenced by existing research, and explores its potential as a prognostic marker for these diseases." (PMID 40452932, 2025). "By influencing key processes such as pyroptosis, cell proliferation, and immune modulation, GSDMB significantly impacts cancer progression, metastasis, and inflammatory pathologies." (PMID 40452932, 2025). "Double immunofluorescence staining showed that GSDMB+ immune cells in cancer stroma were mostly CD68+ cells and S100A8+ cells." (PMID 38711020, 2024). "The expression of GSDMB experiences a marked upsurge in GC, implicating the potential role of GSDMB in modulating cancer cell proliferation." (PMID 38304430, 2024). "In cancer cells, GSDMB expression is linked to the systemic inflammatory response, TIM, and decreased cancer progression." (PMID 38711020, 2024). "GSDMB was expressed in the cytoplasm, membrane, and nucleus in both normal epithelial cells and cancer cells." (PMID 38711020, 2024). "Intriguingly, as an executor of pyroptosis, many studies have reported that GSDMB expression is upregulated in cancer tissues." (PMID 38711020, 2024). "The expression of GSDMB in cancer cells is related to myeloid derived inflammatory cells rather than lymphocytes in TIM." (PMID 38711020, 2024). "In this study, we evaluated the expression of GSDMB in the membrane, cytoplasm, and nucleus of cancer cells, as well as in the TIM, and assessed the distribution and density of some types of immune cells in 267 CRC samples with follow-up information." (PMID 38711020, 2024). "The rate of positive nuclear GSDMB expression in normal epithelial cells was higher than that in cancer cells." (PMID 38711020, 2024). "As a result, these GSDMs primarily function in basic immune responses and do not exhibit the specialized roles seen in mammals, such as GSDMA’s involvement in cancer suppression and GSDMB’s regulation of inflammatory processes." (PMID 39735183, 2024). "In the hospital samples, the positive rates of total GSDMB expression in cancer and adjacent normal tissue were 90.7% (68/75) and 96.0% (72/75) respectively, which is similar to ours (84.6% and 91.5%, respectively, data not shown)." (PMID 38711020, 2024). "GSDMB, which shows increased expression in inflammatory diseases and certain cancers, can be activated by granzyme A secreted by immune cells." (PMID 39735183, 2024). "The positive GSDMB expression rates in the cell membrane, cytoplasm and nucleus were 27.3% (73/267), 79.8% (213/267), and 67.8% (181/267), respectively, in cancer cells." (PMID 38711020, 2024). "An increasing number of studies have found that GZMA, derived from cytotoxic T lymphocytes, cleaves GSDMB, leading to the formation of pores on the cell membrane and inducing pyroptosis in cancer cells expressing GSDMB." (PMID 39735183, 2024). "In all of the mentioned disorders, tissue overexpression of GSDMB is observed, including in several cancers (e.g., breast, cervical, gastrointestinal tract)." (PMID 38693919, 2024). "More data are needed to establish the effect of GSDMB expression in cancer cells on systemic inflammation." (PMID 38711020, 2024). "Most importantly, GSDMB supports proliferation and motility, which is particularly important for cancer cells." (PMID 37771587, 2023). "The promoter methylation levels of GSDMB have distinct effects on protein expression in different cancers." (PMID 37064151, 2023).
cancer (continued). "In a context of immune activation, NK and T-cells secrete GZMA, which in turn cleaves GSDMB either at the K229 or K244 residues within cancer cells, inducing pyroptosis and the subsequent antitumoral immune response." (PMID 36899106, 2023). "Here, we conducted a comprehensive screening of GSDMB expression, genetic alteration, immune infiltration, and possible related pathways in previously published pan-cancer databases." (PMID 37064151, 2023). "Outside of inflammatory diseases there is a well-established literature base for the role of GSDMB expression changes and in promoting invasion and metastatic potential in cancer." (PMID 37266429, 2023). "Summarizing, our results have important implications for understanding the complex roles of GSDMB isoforms in cancer or other pathologies and for the future design of GSDMB-targeted therapies." (PMID 36899106, 2023). "Releasing GSDMB pyroptosis specifically in cancer cells can be a promising antitumor therapeutic approach." (PMID 36899106, 2023). "This pioneering study clarifies the mechanisms of GSDMB pyroptosis and highlight the distinct relevance of GSDMB isoforms in cancer biology." (PMID 36899106, 2023). "Similar to GSDME, GSDMB is cleaved by granzyme A to unleash its pore-forming activity, resulting in the killing of GSDMB-positive cancer cells through pyroptosis." (PMID 37134086, 2023). "Two immunomodulators, TNFSF14 and TNFRSF25, were found to regulate GSDMB gene expression in cancers." (PMID 37064151, 2023). "Most importantly, GSDMB expression is increased in different types of cancer, including breast, cervical, hepatic, and gastrointestinal cancer, and its high mRNA expression is associated with poor prognosis in breast cancer." (PMID 37771587, 2023). "When the GSDMB pore-forming N-terminal domain is released by Granzyme-A cleavage, it provokes cancer cell death, but uncleaved GSDMB promotes multiple pro-tumoral effects (invasion, metastasis, and drug resistance)." (PMID 36899106, 2023). "Summarizing, our data contributes to clarify the mechanisms of GSDMB cell death and highlight the differential role of GSDMB isoforms in cancer biology." (PMID 36899106, 2023). "For instance, high expression of GSDMB correlates with either better or worse survival rates in patients in a cancer-type-dependent manner." (PMID 36742298, 2023). "Further corroborating the effect of NE cleavage in cancer pyroptosis, NE cleaves GSDMB in SKBR3 cells and releases the pyroptotic-inactive p23 NT fragment." (PMID 36899106, 2023). "This newly developed nanomedicine specifically and significantly suppressed GSDMB function and inhibited cancer cell migration and metastasis." (PMID 38016064, 2023). "It has been demonstrated that GSDMB is located in amplicons and that these genomic regions are frequently amplified in cancer development." (PMID 36163033, 2022). "On the one hand, similar to other GSDM family members, the released/activated GSDMB NT domain has pore-forming activity on biological membranes that can provoke lytic cell death of normal, cancer cells and intracellular bacteria." (PMID 36163066, 2022). "Heterologous overexpression of GZMA-cleavable human GSDMB in mouse cancer cells accelerates the elimination of tumors in vivo." (PMID 35673561, 2022). "Recently, granzyme A was also shown to trigger pyroptosis of cancer cells through cleavage of the pore-forming protein, gasdermin B." (PMID 35401556, 2022). "GSDMB can also be activated by caspase-3, 6, and 7 in a manner similar to GSDMD, and some researches have shown that GSDMB overexpression occurred in several kinds of cancers." (PMID 35132346, 2022). "GSDMB expression was increased in many cancers, such as breast, cervical, and hepatic cancer, in which high expression was linked to poor prognosis." (PMID 35664308, 2022). "High expressions of GSDMA, GSDMB and GSDMC were associated with subtype C1 (Wound healing), C2 (INF-r dominant) and C6, indicating a cancer promoter role of these three members." (PMID 35164740, 2022).
cancer (continued). "Meanwhile, GSDMD and GSDMB were differentially expressed in most tumors, and all evidence supported their involvement in the induction of the pyroptosis process in cancer, which also increased the predictive value of UCEC." (PMID 35574367, 2022). "The GSDMB is highly expressed in cancer tissues and is connected with poor prognosis by relapse-free survival, and therefore has been used as a potential novel prognostic marker." (PMID 35488327, 2022). "Taken together, our results reveal that the autophagy inhibition reverses, at least in part, the resistance to lapatinib mediated by GSDMB over-expression in HER2 cancer cells." (PMID 36163066, 2022). "The data demonstrated that the mRNA expression of GSDMB was expressed in an abnormal way throughout different types of cancers." (PMID 34957313, 2021). "For example, lymphocyte-derived granzyme A (GZMA) cleaves gasdermin B (GSDMB) at the linker, which unleashes its pore-forming activity and results in pyroptotic cell death of GSDMB-expressing cancer cells." (PMID 33941231, 2021). "More recently, it has been shown that GzmA cleaves Gasdermin B (GSDMB) to trigger pyroptosis of target cancer cells." (PMID 34413857, 2021). "The complete working set contained 33 types of cancer of which the mRNA expression pattern of GSDMB was evaluated." (PMID 34957313, 2021). "In comparison to normal tissues, GSDMB was significantly upregulated in 12 out of 33 cancer types and downregulated in 15 out of 33 cancer types." (PMID 34957313, 2021). "The highly expressed GSDMB significantly promotes cancer cell migration and develops cancer cell resistance to anti-HER2 therapies." (PMID 34421915, 2021). "Expression of human GSDMB or GSDME sensitized cancer cells to cytotoxic lymphocyte-induced pyroptosis in a granzyme-dependent manner." (PMID 33406603, 2021). "The N-terminal domain of GSDMB could link up with sulfatide distinctively, and since the overexpression of sulfatide is often associated with the progression of cancer, it suggests that GSDMB may have a significant function in cancer cell metastasis and migration." (PMID 34957313, 2021). "In our research, according to the pan-cancer analysis, we demonstrated that GSDMB mRNA is atypically expressed in different types of cancers." (PMID 34957313, 2021). "Next, we assessed the influence of GSDMB gene amplification and/or expression in the therapeutic response of this cancer subtype." (PMID 27462779, 2016). "Although these other members have been implicated in the development and progression of some diseases, the role of GSDMB in cancer is only now beginning to emerge." (PMID 27462779, 2016). "In this study, we developed a therapeutic vector that expresses HSVtk in cancer cells, utilizing a regulatory region of the gasdermin B gene (GSDMB)." (PMID 26016667, 2015). "Because GSDMB is expressed in many types of cancer, including GC, it is likely that the gene contains a regulatory region that is utilized for therapy of occult PD through cancer cell-specific expression of cytotoxic genes." (PMID 26016667, 2015). "To determine if GSDMB over-expression increases cancer cell invasion we performed matrigel-coated Boyden chamber invasion assays." (PMID 24675552, 2014). "GSDMB has also been shown to be important in cancer pathogenesis, with alternative splicing of the gene being involved in gastrointestinal and hepatic cancers." (PMID 24044605, 2013). "Gene expression of GSDMA and GSDMD was frequently suppressed, and GSDMB was overexpressed in cancer cell lines and/or cancer tissue specimens." (PMID 23979942, 2013). "For instance, overexpression of human GSDM family genes, except for GSDMB, induces cell-growth inhibition in cancer cell lines." (PMID 23979942, 2013). "GZMA from CTLs can cleave GSDMB, causing pyroptosis in GSDMB-positive cancer cells, though GSDMB is not expressed in all human tissues and is absent in mice." (PMID 40806716, 2025).
cancer (continued). "GSDMB’s importance lies in its multifaceted roles in cancer biology and inflammatory diseases." (PMID 40452932, 2025). "Additionally, caspase-8 can cleave GSDMC to trigger pyroptosis in cancer cells, while apoptotic caspases-3, -6, and -7 can cleave GSDMB, releasing its pore-forming N-terminal domain and inducing pyroptosis." (PMID 40806716, 2025). "A recent study showed a novel link between GSDMB and immunotherapy responsiveness in cancer." (PMID 41291696, 2025). "Meanwhile, various GSDMB isoforms cleaved by specific proteases have different effects on pyroptosis regulation, and only GSDMB isoforms containing exon 6 translation can induce cancer cell pyroptosis." (PMID 38695942, 2024). "Furthermore, we found that patients with cytoplasmic or nuclear GSDMB expression in cancer cells more often benefited from 5-Fu based chemotherapy." (PMID 38711020, 2024). "GSDMB is frequently up-regulated and has a complex role in cancer." (PMID 39062587, 2024). "However, GSDMB expression in immune cells has different effects on cancer progression from that in cancer cells." (PMID 38711020, 2024). "However, in commercial samples, the positive rates of GSDMB expression were 63.2% (98/155) in cancer and 52.9% (82/155) in adjacent normal tissue, which were much lower than those for their hospital samples and our samples." (PMID 38711020, 2024). "Recent studies have found that GSDMB could inhibit epithelial cell proliferation and motility, suggesting that epithelial-derived GSDMB has a protective function from cancer." (PMID 39062587, 2024). "A GSDMB-dependent cellular function study suggested that GSDMB-expressing intestinal epithelial cells (IECs) have a protective effect during gastrointestinal inflammatory infection and cancer." (PMID 39062587, 2024). "GSDMB expression in cancer cells was scored in the membrane, cytoplasm, and nucleus respectively." (PMID 38711020, 2024). "In conclusion, GSDMB is expressed in both cancer and immune cells, but its effects on cancer progression may be complex and possibly disparate." (PMID 38711020, 2024). "GSDMB plays complex biological roles since it can exhibit either cell-death dependent and independent functions in diverse pathological conditions such as enterobacteria infection, asthma, inflammatory bowel diseases, and cancer." (PMID 36899106, 2023). "GSDMB is significantly involved in many signal pathways, including cytokine–cytokine receptor interaction, sphingolipid metabolism, IBD, and other immune pathways, which are implicated in cancer and neurodegenerative diseases." (PMID 37064151, 2023). "GSDMA and GSDMB are similarly silenced by methylation in some cancer cell lines." (PMID 36742298, 2023). "As GSDMB has become a new therapeutic target for cancer in combination with different immunotherapies, this study suggests that it might be especially efficacious in KIRC patients." (PMID 37064151, 2023). "Therefore, we assessed the potential correlation between GSDMB expression and immune cell infiltration in different cancers." (PMID 37064151, 2023). "In cancer, previous evidences suggested that GSDMB isoforms also exhibit different effects in vivo." (PMID 36899106, 2023). "Firstly, reduced expression of both gasdermin B and E have been identified in many cancers." (PMID 35401556, 2022). "Besides, this work provides a new therapeutic approach for HER2/GSDMB + cancers, characterized by poor clinical outcome." (PMID 36163066, 2022). "Interestingly, GSDMB is regarded as an oncogene because it is overexpressed in several cancers including gastric cancer, breast cancer and cervical cancer." (PMID 36189207, 2022). "The multifunctional protein GSDMB plays complex roles in inflammatory pathologies and cancer." (PMID 36163066, 2022). "Additionally, the GSDME and GSDMB are cleaved directly by granzyme in cancer cells also, in turn, enhancing anticancer immunity." (PMID 36119049, 2022).